TSPY4 (testis specific protein Y-linked 4)
Description:
May be involved in sperm differentiation and proliferation.
Tractability: PROTAC: ubiquitination databases record sites on it.
Gene: Protein-coding gene on chromosome Y (9,337,464 to 9,340,284, forward strand). Ensembl gene ENSG00000233803.
Subcellular location: Cytoplasm; Nucleus
Subcellular location (Human Protein Atlas): Cytosol
Gene Ontology:
Biological process: nucleosome assembly
Cellular component: chromatin; cytoplasm; nucleus
Homologues: Orthologues: macaque TSPY2 (70% identical), zebrafish tspy (28% identical), Drosophila melanogaster Set (22% identical), Caenorhabditis elegans spr-2 (19% identical), Drosophila melanogaster Nap1 (14% identical), Caenorhabditis elegans nap-1 (14% identical), Drosophila melanogaster CG3708 (12% identical), Drosophila melanogaster mil (12% identical), zebrafish nap1l4a (12% identical). Paralogues in human: TSPY9 (99% identical), TSPY10 (98% identical), TSPY3 (98% identical), TSPY1 (97% identical), TSPY2 (97% identical), TSPY8 (97% identical), TSPYL1 (33% identical), TSPYL4 (32% identical), TSPYL5 (31% identical), TSPYL2 (30% identical), TSPYL6 (28% identical), SET (25% identical), and 6 more.
Diseases named in the same sentence as TSPY4 in open-access papers:
TSPY4 is named in the same sentence as 4 diseases in open-access papers, as found by Europe PMC text mining. Sharing a sentence is not in itself a finding about the gene and the disease. The quoted sentences say what the papers report.
cryptorchidism (1 paper, 2019). The failure of one or both testes of a male fetus to descend from the abdomen into the scrotum during the late part of pregnancy. "Our findings implicate Y-chromosomal genes, including USP9Y, UTY, TXLNGY, RBMY1B, RBMY1E, RBMY1J and TSPY4, some of which are known to be important for spermatogenesis, in the curative hormonal treatment of cryptorchidism-induced infertility." (PMID 31171972, 2019).
infectious disease (1 paper, 2023). A disorder directly resulting from the presence and activity of a microbial, viral, or parasitic agent in humans. "TSPY4, OPN1LW, CARF, CCDC14, HNRNPCL4, SSX2B genes need further exploration as it has not been identified in any infectious disease, including the recent COVID-19 pandemic." (PMID 37644081, 2023).
TSPY4 also shares sentences with these, for which no sentence is quoted: Azoospermia (1 paper); Infertility (1).